MTOR (mechanistic target of rapamycin kinase)
Diseases named in the same sentence as MTOR in open-access papers (continued):
Sharing a sentence is not in itself a finding about the gene and the disease.
breast cancer (continued). "Further experimental studies have found that ERS induction, in turn, induced autophagy and apoptosis in breast cancer cell lines under the regulation of the Akt/mTOR pathway and IRE1/JNK/beclin-1, with the authors suggesting that ERS promotion in breast cancer may be a therapeutic target of TNBC." (PMID 27494867, 2016). "In both RCC and breast cancer, PKM2 was overexpressed in cancer tissues, alongside with elevated phosphorylation of S202/203, phosphorylation of mTOR and phosphorylation of 4EBP that signaled activation of mTOR signaling, and elevated p62 that signaled inhibited autophagy." (PMID 26876154, 2016). "Everolimus and other PI3K/Akt/mTOR inhibitors are known to induce autophagy in both solid and blood tumors; however, to our knowledge, this phenomenon has not been reported in breast cancer cells." (PMID 27421652, 2016). "In turn, sensitivity to rosiglitazone could be explained by the fact that MDA-MB-231 breast cancer cells express very high levels of ACSL4 and, as shown in the results above, ACSL4 affects the up and downregulators of mTOR and regulates mTORC1 and mTORC2 activities." (PMID 26536660, 2015). "However, in breast cancer and melanoma cell lines examined in our study let-7a did not alter the phosphorylation status of mTOR nor of its downstream component S6." (PMID 25669981, 2015). "Herein, to conclusively address the role of mTOR in PRL-3 signalling, we thoroughly examined the correlation of PRL-3 with mTOR activity in: 1) human clinical cancer samples, 2) a mouse model of spontaneous mammary tumour development, and 3) a panel of transgenic tumour cell lines." (PMID 26597054, 2015). "However, the murine breast cancer 4T1 cells showed both decreased mitochondrial ATP production, and no detectable mTOR translocation to mitochondria after radiation." (PMID 25807077, 2015). "Importantly, blocking mTOR activity largely abolished the promoting effect of LIF on breast cancer metastasis, suggesting that the activation of mTOR pathway mediates the promoting effect of LIF on breast cancer tumorigenesis and metastasis." (PMID 24553191, 2014). "Likewise additional clinical trials with HER2+ breast cancer patients and the inclusion of PI3K/mTOR inhibitors may improve therapy of the HER2 inhibitors." (PMID 25051360, 2014). "In addition, estrogen stimulation of breast cancer cells immediately upregulates intracellular kinase signaling, suggesting nongenomic signaling through cytoplasmic or membrane-bound ER to be involved in activation of PI3K/AKT/mTOR signaling." (PMID 25209360, 2014). "However, the ability of estrogen to regulate phosphorylation of mTOR in breast cancer cells has not been reported." (PMID 24887419, 2014). "For example, Tamoxifen resistant breast cancer cells with overexpressed/activated v-akt murine thymoma viral oncogene homolog (AKT) or lack of phosphatase and tensin homologue (PTEN) may benefit from Rapamycin treatment, a highly specific mTOR inhibitor." (PMID 23341997, 2013). "The mTOR inhibitor everolimus was recently approved by the Food and Drug Administration for treatment of aromatase inhibitor-resistant estrogen receptor positive breast cancer, and a number of PI3-kinase or Akt inhibitors are under active clinical investigation in breast cancer." (PMID 23237847, 2013). "Inhibitors of mTOR signalling may have a clinical potential in the management of several malignancies, not least as a complement to ER-targeted therapies in breast cancer." (PMID 24131622, 2013). "In addition, oestrogen stimulation of breast cancer cells immediately upregulates intracellular kinase signalling, suggesting nongenomic signalling through cytoplasmic or membrane bound ER to be involved in activation of PI3K/AKT/mTOR signalling." (PMID 24131622, 2013).
breast cancer (continued). "Several of the genes involved are also in signalling pathways relevant to breast cancer: ERBB2, NRIP1 and BCAS3 are involved in estrogen receptor function and APPBP2 with androgen receptor; while TAOK1 and SKAP1 are involved in MAPK signalling and DEPDC6/DEPTOR regulates mTOR signalling." (PMID 23260012, 2012). "However, the therapeutic effects of EGFR and mTOR inhibitors in combination have not yet been broadly assessed in HER2 overexpressing breast cancers with different TZ sensitivity." (PMID 21961653, 2011). "However, the mechanism by which OPN regulates mTOR/p70S6 kinase activation in breast cancer cells is not well defined." (PMID 20459645, 2010). "Downregulation of the mTOR inhibitor TSC1 in effusion may lead to subsequent activation of mTORC1 at this site of metastasis, suggesting that this signaling pathway may be altered along tumor progression in breast carcinoma." (PMID 19680458, 2010). "Pin1 inhibition greatly increased the sensitivity of Her2-positive breast cancer cells to the mTOR inhibitor Rapamycin, while it did not increase their sensitivity to Trastuzumab, suggesting that Pin1 might act on Her2 signaling." (PMID 19077306, 2008). "Therefore, breast cancer cell lines BT-474, MCF-7, MDA-361, MDA-436 and SK-BR-3 were treated with these inhibitors to compare transcriptional signatures responsive to both RPS6KB1 and PI3K/mTOR pathway inhibitions." (PMID 18652687, 2008). "Patients with tumours expressing activated PLD1/mTOR signalling may be sensitive to rapamycin-based therapies; however, it has been shown that high levels of PLD1 confers rapamycin resistance in MDA-MB-231 breast cancer cells in vitro." (PMID 17726467, 2007). "Therefore, to evaluate if pharmacological inhibition of mTOR could increase sensitivity to T-DM1, we evaluated the growth inhibitory activity of T-DM1 in combination with the mTORC1 inhibitor everolimus in four HER2-positive breast cancer cell lines." (PMID 40165206, 2025). "Furthermore, our microarray analysis of the profile of genes related to the PI3K/AKT/mTOR pathway and the miRNAs involved in regulating their expression indicated that also the MAPK3 gene plays an important role in the cascade in question in the context of breast cancer." (PMID 39850811, 2024). "Inhibition of three enzymes that produce H2S in breast cancer (BC) cells significantly promotes apoptosis in the mitochondrial pathway, the mechanism is that lower intracellular levels of H2S inhibit phosphorylation of the PI3K/Akt/mTOR signaling pathway." (PMID 38448410, 2024). "Moreover, SLC7A11 was reported to be related to PI3K/AKT/mTOR signaling pathway in cancers, such as gastric cancer, glioma, pancreatic carcinoma, neuroendocrine tumors, but the interaction has not been clarified in breast cancer." (PMID 39868374, 2024). "However, in contrast to primary tumor, inhibition of mTOR signaling did not inhibit lung metastases due to the lower activity of mTOR and proliferation activity in lung cells compared to mammary tumors; as a result, Col1a1tmJae/+ mice continued to sustain higher metastatic burdens." (PMID 37468874, 2023). "In addition, in breast cancer cells, TRPC5 activation promotes autophagy and chemoresistance via the Ca2+/calmodulin-dependent protein kinase beta/adenosine monophosphate-activated protein kinase alpha/mechanistic target of rapamycin (CaMKKβ/AMPKα/mTOR) pathway." (PMID 37892239, 2023). "Despite the absence of SCRIB mutations in clinical breast cancer, over-expression resulting from amplifications in its gene or other mechanisms may increase the cytoplasmic localization of the protein and activate the PI3K/AKT/mTOR pathway." (PMID 36675340, 2023). "Moreover, CUR interferes with the PI3K/Akt/mTOR pathway through its regulatory role on key molecule players of AKT, PTEN, HER2, and mTOR, which may facilitate the inhibition of cellular growth, invasion, and metastasis in breast cancer." (PMID 35216255, 2022).
breast cancer (continued). "Based on these results showing an apparent relationship between AKT/mTOR signaling and ATRAP expression in breast cancer cells, we next used the mTOR inhibitor rapamycin (20 nM) to examine whether AKT/mTOR signaling was required for ATRAP-mediated breast cancer progression." (PMID 35414770, 2022). "Additionally, neither the active forms of lysosomal proteases cathepsin D nor the MTOR pathway were significantly altered in this process, indicating that autolysosomal degradation upon NUPR1 depletion is independent of the MTOR pathway in TamR breast cancer cells." (PMID 33542201, 2021). "Similarly, BELLE-3, a randomized, double-blind, placebo-controlled, multicenter, phase III study, evaluated the safety and efficacy of buparlisib plus fulvestrant in patients with advanced HR+ HER2 negative (HER2−) breast cancer who were pretreated with endocrine therapy and mTOR inhibition." (PMID 34769309, 2021). "Furthermore, we aim to elucidate whether there is a synergistic effect of IBL-302 and trastuzumab in breast cancer models, including in vitro models of trastuzumab resistance, given the published role of PI3K/AKT/mTOR, and more recently of PIM kinase signalling in trastuzumab resistance." (PMID 32042115, 2020). "Our results in the present study suggest that the PI3K-AKT-mTOR pathway is crucial in the adipocyte-mediated breast cancer progression and that dual inhibitors targeting PI3K and mTOR such as BEZ235 could be a good option to inhibit the obesity-breast cancer link." (PMID 32201525, 2020). "Breast cancer with 8p11.23 inhibition of the amplified EIF4EBP1 may increase the dependency of the cancer cells to the activity of mTOR in order to secure active protein production, and thus may make these cells sensitive to inhibition of mTOR by drugs such as everolimus." (PMID 32987805, 2020). "This suggests that acquired resistance to AIs is related to the PI3K/Akt/mTOR signaling pathway, a major regulator of the cell cycle, and that a SERD or SERM plus a targeted therapy that inhibits the PI3K/Akt/mTOR pathway may have superior efficacy for breast cancer with secondary resistance to AIs." (PMID 32099680, 2020). "Therefore, we suspect PRR14’s function in breast cancer may not be limited to the activation of the PI3K/AKT/mTOR signaling pathway." (PMID 32541902, 2020). "In addition, breast cancer cells lacking BRCA1 expression were more sensitive to mTOR inhibition." (PMID 31771139, 2019). "In breast cancer cells, miR-17-5p negatively regulates the expression of phosphatase and tensin homolog, PTEN, and the activation of PTEN inhibits the PI3K/AKT/mTOR signaling pathway, suggesting that the overexpression of miR-17-5p may promote the PI3K/AKT/mTOR signaling pathway." (PMID 29713287, 2018). "Combined with two other breast cancer and lung adenocarcinoma studies indicating the influence of Gabra3 on the AKT/mTOR, and JNK pathways, we suggest that the regulatory role of miR-92b-3p in the AKT/mTOR and JNK pathways might be indirect and Gabra3-dependent." (PMID 29078789, 2017). "Also, out of a total of 95 breast cancer samples, there were 5 breast-cancer samples which did not have mTOR-pathway activation, and all 5 (100%) of these had PIK3CA and PTEN mutations compared to 51/90 (57%) in the breast-cancer samples with mTOR-pathway activation (χ2p=0.0134)." (PMID 29137436, 2017). "Furthermore, we are the first to report that phenformin not only activates AMPK but also inactivates mTOR and p70s6k, which act downstream of AMPK, suggesting that the AMPK/mTOR/p70s6k axis may be a major target of phenformin in inducing breast cancer apoptosis." (PMID 26114294, 2015). "We found that inhibitors targeting the same PI3K/mTOR pathway sensitize everolimus resistant breast cancer cell lines to growth inhibition, regardless of whether they are dual PI3K/mTOR kinase inhibitors (BEZ235 and GSK2126458) or an mTOR kinase specific inhibitor (AZD8055)." (PMID 26148118, 2015).
breast cancer (continued). "Considering our observations in ERα-positive early breast cancer patients, it is not likely that PIK3CA hotspot mutation status by itself would be a suitable companion diagnostic predicting benefit from the putative use of PI3K/AKT/mTOR inhibitors in the adjuvant setting." (PMID 24467828, 2014). "The published data suggest that the combined effects of the PI3K/mTOR and MEK pathways may be important for cancer growth, pointing to the possibility that combined blockage of these two signaling pathways may be an important component of successful breast cancer treatment strategies." (PMID 25170609, 2014). "Therefore, the sustained response experienced by our patient may be due to the reversion of hormone resistance by sirolimus, rather than to the activity of the mTOR inhibitor alone, in parallel to breast cancer." (PMID 25104960, 2014). "Importantly, a dose-dependent effect of CR on mTOR inhibition mediated by AMPK was also observed in a rat model of breast cancer, suggesting that fasting might have similarly negative effects on DNA repair capacity in mammary tumors as rapamycin." (PMID 24436017, 2014). "This is not seen and may suggest alternate receptor and PIK3CA/mTOR interaction in male breast cancer or a dose-based relationship differentiated by male cancers with low estrogen at one end of the spectrum and higher levels of estrogen in females at the opposite end." (PMID 23971979, 2013). "Thus, combining drugs that inhibit function of EGFR/HER2 with dual PI3K/mTOR and MEK pathway inhibitors in order to abolish compensatory mechanisms may eliminate cancer cell survival and perhaps improve therapeutic effects in HER2-positive breast cancers." (PMID 21961653, 2011). "Moreover, siRNA against c-Src, Akt and mTOR was observed to inhibit the phosphorylation of 4E-BP1 and p70S6K as well as exhibited blunted HIF-1α expression in response to E2, suggesting the importance of mTOR signalling in the elevated HIF-1α levels in breast cancer cells." (PMID 21897387, 2011). "In addition, our data show that α-TEA not only enhances rapamycin suppression of mTOR and induction of apoptosis, but also suppresses rapamycin-mediated feedback activation of AKT, providing a rationale for developing a combination regimen of mTOR+α-TEA for breast cancer treatment." (PMID 21119656, 2011). "Collectively, these findings suggest that the PI3K/AKT/mTOR, MAPK, and collagen-related pathways play a particularly prominent role in the aggressive behavior of TNBC and Non-luminal HER2+ breast cancer subtypes." (PMID 39850811, 2024). "ERα-positive breast cancer patients with increased TUBB showed worse prognosis, possibly through the activation of the TSC/mTOR pathway, whereas ERα-negative breast cancer patients with increased TUBB mRNA showed better prognosis." (PMID 36140469, 2022). "In the present study, we were interested in the effects of SA in ER-positive (MCF-7) and -negative (MDA-MB-231 and BT-20) breast cancer cells in connection with the activation of EGFR expression and the AKT/mTOR pathway." (PMID 35053341, 2022). "We tested mTORC1 activation in the HPR-knockdown breast cancer cells and found that HPR depletion significantly decreased the phosphorylation of 70S6K (Thr389) but not mTOR (Ser2448)." (PMID 34462427, 2021). "After GEM treatment, mTOR signaling was enhanced in PANC-1 pancreas cancer cells and was not affected in MDA-MB-231 breast cancer cells, thus contributing to chemoresistance." (PMID 34959348, 2021).
breast cancer (continued). "No mutual correlation was observed between mTOR (e.g. p-S6) and MAPK signalling, confirming that in the majority of breast cancer cells these signalling pathways are not significantly co-activated." (PMID 33790302, 2021). "We here observe that, in breast cancer cells, CSNK1G2-silenced cells lead to the suppression of not only PI3K/AKT/mTOR/S6K but also ERK." (PMID 33861751, 2021). "Additionally, mTOR-independent non-canonical autophagy was reported to provide stress resistance to neuroblastoma and breast cancer cells, suggesting selenite may induce protective autophagy in HCT116 cells via AMPK/GABARAPL-1 related pathways without affecting mTOR." (PMID 35201430, 2021). "In this study, we observed a negative correlation between members of the AKT/mTOR pathway and CHOP and ATF4 in breast cancer, both of which are downstream of PERK." (PMID 32508655, 2020). "In ERα-positive breast cancer cells, LKB1 binds to ERα and in doing so makes its cytosolic pool not adequate to activate AMPK signaling, thus maintaining mTOR signaling and sustaining cell growth." (PMID 33511117, 2020). "We observed a negative correlation between the AKT/mTOR pathway members and CHOP and ATF4 in breast cancer." (PMID 32508655, 2020). "We further demonstrated that ALOX5 is important for breast cancer biological activities with the predominant roles in growth and migration, likely through RhoA, focal adhesion, and PI3K/Akt/mTOR signaling but not epithelial mesenchymal transition (EMT)." (PMID 33224971, 2020). "In a breast cancer cell line, under low-glucose conditions, metformin significantly decreased the phosphorylation of AKT and various targets of mTOR, whereas phospho-AMPK was not significantly altered." (PMID 32825834, 2020). "A similar outcome was seen in a multicentre Phase I/Ib trial in advanced solid tumours, including breast cancer, where PI3K/mTOR inhibition by BEZ235 was not sufficient to achieve an adequate antitumor effect with a favourable safety profile." (PMID 35582282, 2019). "The results showed that, consistent with our gene chip result, TIPE1 preferentially inhibited the ERK phosphorylation (p-ERK), but not p-p65, p-mTOR, p-S6, or p-MEK, in breast cancer cells." (PMID 31179241, 2019). "In another Phase I/IB study of BEZ235 in patients with advanced solid tumors including those with advanced breast cancer, the inhibition of PI3K/mTOR was not sufficient and adverse effects were prevalent." (PMID 31817676, 2019). "The results showed that, consistent with our gene chip result, TIPE1 almost completely inhibited ERK phosphorylation (p-ERK) but not p-p65, p-mTOR, pS6, or p-MEK in breast cancer cells." (PMID 31179241, 2019). "ERα negative breast cancer cells proliferate independently of oestrogen signalling through other signalling pathways such as the EGFR, and downstream PI3K/Akt/mTOR, NF-κB signalling pathways." (PMID 29564971, 2018). "Summary of phase III clinical trial results for PI3K and mTOR inhibitors in metastatic HR positive, HER2 negative breast cancer." (PMID 30148117, 2018). "The selective cytotoxicity of Oridonin in p-AKTHigh breast cancer cells provides a therapeutic advantage that cannot be achieved by the pan PI3K inhibitor BKM120, dual PI3K/mTOR inhibitor BEZ235, AKT inhibitor MK2206." (PMID 29844859, 2018). "This study compared the effects of treatment with two mTOR inhibitors, PP242 and RAD001, with and without irradiation on the selective translation of mRNAs in an inflammatory breast cancer cell line." (PMID 30409155, 2018). "Everolimus, a mTOR inhibitors, has been approved by FDA for the treatment of hormone receptors positive and HER2 negative advanced postmenopausal breast cancer patients, hoping to overcome or slowdown the development of endocrine resistance." (PMID 29453409, 2018).